SIRT2 (sirtuin 2)
Diseases named in the same sentence as SIRT2 in open-access papers (continued):
Sharing a sentence is not in itself a finding about the gene and the disease.
cancer (continued). "Among the cytosolic deacetylases responsible for the deacetylation of nonhistone proteins (i.e., HDAC6, SIRT1, and SIRT2), the expression of SIRT1/2 was considerably higher in cancer cells (i.e., A549 and HCC1806 cells) than in normal tissue cells (i.e., BEAS-2B and HMLE cells)." (PMID 38649663, 2024).
tumor (200 papers, 2011 to 2026). "Secretion of SIRT2 from activated myeloid cells in tumour microenvironments has been reported and associated with the promotion of metastasis formation through the deacetylation of extracellular proteins." (PMID 41013715, 2025). "This targeted delivery approach is designed to reduce the risk of unintended off-target effects of inactivating SIRT2 in tissues where it functions as a tumor suppressor." (PMID 40762838, 2025). "Depending on the mutational status and tumor type, SIRT1 and SIRT2 can influence both tumor promotion and suppression." (PMID 41333420, 2025). "Published data showed that SIRT2 inhibits not only the humoral response but also macrophages, myeloid-derived cells, and tumor-associated neutrophils in tumor tissues." (PMID 40149343, 2025). "Quantification of tumor-associated macrophages (TAMs) showed that Sirt2−/− HCCs had significantly fewer TAMs than Sirt2+/+ HCCs." (PMID 37628798, 2023). "SIRT2-deficient murine T cells and SIRT2 blockaded human tumor-infiltrating lymphocytes showed increased glycolysis and oxidative phosphorylation, enhanced proliferation and effector functions and thereby superior antitumor activity." (PMID 36993975, 2023). "Tumor‐associated macrophages seemed to express a higher level of SIRT2 protein than non‐tumor associated macrophages." (PMID 36453571, 2023). "Significantly, HIF-1α degradation, which is connected to SIRT2 activity, underlines the tumor suppressor role proposed for SIRT2 in many studies." (PMID 35745656, 2022). "By transfecting wild‐type or dead‐enzyme mutants of SIRT1 or SIRT2 into tumour cells, we found that the loss of SIRT2 deacetylase activity resulted in consistent levels of LIFR‐K620 acetylation." (PMID 35172032, 2022). "Our results identify NK cells as a key player in SIRT2-mediated tumor progression, suggesting that tumors generated in Sirt2-KI mice develop more aggressively due to a deficiency of NK cells infiltrating in TME." (PMID 34155309, 2021). "Elevated Sirtuin 2 (SIRT2) was found to be associated with poor prognosis in CRC patients via its participation in tumor angiogenesis." (PMID 34899841, 2021). "In line with our finding, TCGA and GEO database (GSE40275) mining showed that the expression of SIRT2 was much lower in tumor samples of high-risk NSCLC patients." (PMID 32104503, 2020). "SIRT2, a nicotinamide adenine dinucleotide+-dependent deacetylase, has been proposed to be a tumor suppressor associated with aging, the cell cycle, and carcinogenesis." (PMID 30081901, 2018). "More importantly, we showed that high expression of SIRT2 was associated with a poor prognosis and a late tumour stage in CRC." (PMID 30584257, 2018). "SIRT2 has been shown to have a tumor suppressor function and its deletion has been linked to tumorigenesis in murine models and certain tumors." (PMID 29262808, 2017). "In rodents, SIRT2 deficiency induces chromosome alterations and subsequent tumor development, defining SIRT2 as a tumor suppressor." (PMID 23460888, 2013). "Additionally, KAT8’s role in CRC suppression, the tumor resistance mechanisms associated with NBS1 K388 blockade, and the enhanced tumor-suppressive effects observed with the combination of Sirt2 inhibitors and Elesclomol have also been highlighted." (PMID 40484921, 2025). "SIRT2 deficiency causes increased levels of Aurora-A and, consequently, contribute to centrosome amplification, aneuploidy, genomic instability, mitotic cell death, and most importantly, spontaneous tumor formation." (PMID 33014852, 2020). "Interestingly, another report found that a decrease in nuclear SIRT2 was linked with higher tumour metastasis in prostate cancer." (PMID 32042025, 2020).
tumor (continued). "However, in contrast, a previous report has shown that SIRT2-deficient (SIRT2-KO) mice develop certain kinds of tumours through regulation of centrosome amplification." (PMID 30584257, 2018). "In addition, SIRT2 deficiency in Panc-1 cells accelerated xenografts tumor growth in vivo." (PMID 38216561, 2024). "A possible mechanism to explain the profound difference in HCC phenotypes due to a loss of Sirt2 could be in aerobic glycolysis, or the Warburg effect, which is necessary to support tumor growth and cellular proliferation; a loss of Sirt2 could inhibit maximal cellular respiration." (PMID 37628798, 2023). "Moreover, a previous study reported that high SIRT2 expression in advanced tumor tissues is associated with poor prognosis, suggesting that SIRT2 may function as an oncogene." (PMID 35845599, 2022). "However, the function of SIRT2 in tumour angiogenesis and the mechanism underlying the regulation of angiogenesis by SIRT2 are still unknown." (PMID 30584257, 2018). "Regarding SIRT2, we have previously shown that Sirt2-deficient mice develop tumors in several tissues, providing the first strong genetic evidence that SIRT2 may function as a tumor suppressor through its role in regulating the anaphase-promoting complex/cyclosome (APC/C)." (PMID 27637077, 2016). "SIRT2 also functions as a metabolic checkpoint that restrains CD8+ T cell effector metabolism, providing a rationale for combining SIRT2 inhibition with immune checkpoint blockade in metabolically stressed tumor microenvironments." (PMID 41800243, 2026). "The SIRT2 expression level is positively related to cell proliferation in vitro and tumour growth in vivo." (PMID 42009830, 2026). "SIRT2 inhibition in exhausted mouse and human tumor-infiltrating T cells restored TCR responsiveness and antitumor immunity." (PMID 41611868, 2026). "The IHC data further validated that Fn14 overexpression remarkably lessens the SIRT2 protein entry into the nucleus and effectively inhibits the expression of Slug in tumor tissues than that in control tumor tissues." (PMID 40344622, 2025). "As a tumor suppressor, SIRT2 maintains genome stability and prevents oncogenic transformations by regulating the DNA damage response through deacetylating key components like ATRIP (ATR-interacting protein) and CDK9 (Cyclin-dependent kinase 9)." (PMID 40710366, 2025). "In liver cancer, the SIRT2 influences tumor progression through AKT activation, leading to GSK-3 inhibition and elevated β-catenin levels, which drive metastasis." (PMID 41428704, 2025). "While SIRT3, SIRT4, and SIRT6 are poised to induce tumor-suppressive autophagy, others, such as SIRT2 and SIRT7, are likely to stimulate protective autophagic programs that underlie tumor survival and drug resistance." (PMID 41425553, 2025). "Overall, the therapeutic potential of SIRT2 inhibition remains contentious, with some studies suggesting both tumour-promoting and tumour-suppressing effects." (PMID 40136715, 2025). "SIRT2 has pleiotropic activity in tumorigenesis and can act as a tumor promoter or suppressor depending on factors like microenvironment or metabolic requirements of particular cells." (PMID 40149343, 2025). "Taken together, all these results suggest that metformin upregulates PER2, inhibits transplanted xenograft tumor growth in nude mice by inhibiting the SIRT2/G6PD signaling pathway and enhances radiotherapy sensitivity." (PMID 40166471, 2025). "SIRT2′s role remains controversial, with evidence suggesting it can act as either an oncogene or a tumour suppressor across multiple malignancies." (PMID 40136715, 2025). "Therapeutically, SIRT7 or secreted SIRT2 are potential targets for suppressing tumor growth and stimulating immune response." (PMID 41425553, 2025). "SIRT2 can also be inhibitory towards tumor cells by altering the microenvironment and preventing fibroblast activity, angiogenesis, and other processes." (PMID 41304967, 2025).
tumor (continued). "Similar to SIRT1, SIRT2 is also shown to have both tumorigenic and tumor-suppressive roles, but most of the latest evidence corroborates the former role." (PMID 41471349, 2025). "Recent investigations have progressively identified members of the sirtuin family, notably SIRT1 and SIRT2, as key regulators of multiple adaptive strategies used by tumor cells to avoid chemotherapy-induced lethal effects." (PMID 41425553, 2025). "Another study shows that combining a SIRT2-selective inhibitor (compound I) with sorafenib enhanced tumor growth inhibition through increased apoptosis and G0/G1 arrest." (PMID 41471349, 2025). "SIRT2 not only directly influences the cell cycle, but by modulating the tumor microenvironment, it impacts tumor cell invasion and metastasis." (PMID 41304967, 2025). "have found that SIRT2 promotes tumor formation by deacetylating ACLY, thus advancing lipid metabolism, cell migration, and invasion." (PMID 41425553, 2025). "SIRT1, SIRT2, and SIRT7 have been implicated in the development and metastasis of EC, while SIRT6 has been shown to exhibit anti-tumor properties in this context." (PMID 41471349, 2025). "SIRT2, a member of the sirtuin protein family, plays a pivotal role in regulating tumor progression by modulating key metabolic pathways and signaling proteins." (PMID 41428704, 2025). "Many studies have shown that the SIRT2 plays a significant role in regulating tumor progression through the modulation of various substrates involved in metabolic and signaling pathways." (PMID 41428704, 2025). "The pharmacological inhibition of SIRT2 reprograms TILs to increase their metabolic fitness, proliferative capacity, and anti-tumor function in both mouse and human models." (PMID 41425553, 2025). "Our present study adds another piece of evidence that SIRT2 functions as a tumor suppressor by promoting DNA repair by BER for genome stabilization." (PMID 38554113, 2024). "In a word, SIRT2 exerts tumor suppressive effects mainly by regulating cell cycle, DNA damage, cell proliferation, oxidative stress and autophagy." (PMID 39479446, 2024). "This reduction in SIRT2 activity contributes to hyperacetylation, particularly at H3K18, which has been linked to aggressive tumor behavior and therapeutic resistance." (PMID 39796040, 2024). "Overall, the pharmacological inhibition of SIRT2 not only disrupts tumor growth but also impedes metastatic progression." (PMID 39796040, 2024). "In the context of SIRT2, it was observed that SIRT2 was significantly downregulated in primary tumours obtained from CRC patients with liver metastasis (all six patients had low expression) compared to corresponding normal tissues." (PMID 38255946, 2024). "Together, our data reveal that SIRT2 acts as a tumor suppressor by promoting OGG1 transcription and increasing BER efficiency in an ATM/ATR-dependent manner." (PMID 38554113, 2024). "Immunohistochemical analysis of the tumor section exposed to SIRT2-NBs US (+) revealed a marked increase in cell death confirmed using hematoxylin and eosin (H&E), caspase-3, and terminal deoxynucleotidyl transferase (TdT) dUTP Nick-End Labeling (TUNEL) assay." (PMID 39335153, 2024). "The inhibition of SIRT2 was shown to be an important factor in the treatment of various aspects of tumor development and progression, including inhibition of proliferation, invasion, angiogenesis, and metastatic potential." (PMID 36678624, 2023). "Since Sirt2−/− HCCs were more differentiated and had fewer proliferative and immunological markers than Sirt2+/+ HCCs, a loss of Sirt2 resulted in a lesser HCC tumor grade 36 days post-c-MYC induction." (PMID 37628798, 2023). "SIRT2 expression in tumor tissues was significantly higher than normal tissues in GSE11580 datasets." (PMID 37723477, 2023). "SYVN1 has also been proved to promote the growth of tumor cells by promoting the ubiquitination and degradation of tumor suppressor SIRT2." (PMID 37280656, 2023).
tumor (continued). "With histopathological interpretation of the H&E slides, we determined that the tumor tissue architecture of Sirt2−/− HCC tumors was indeed different from that of Sirt2+/+ HCC tumors." (PMID 37628798, 2023). "There is some evidence to suggest that Sirt2 regulates the tumor microenvironment by suppressing regulatory T-cells, promoting invasion through inhibition of the E-cadherin pathway, and increasing the acidity of surrounding tissues." (PMID 37628798, 2023). "SIRT2 was found to promote cell stemness while repressing chemosensitivity in endometrial cancer, whereas others are proved to be tumor suppressors." (PMID 37096064, 2023). "Consistently, IHC staining also exhibited an extracellular distribution pattern of SIRT2 proteins in NSCLC tumor tissue." (PMID 36453571, 2023). "Given our finding that SIRT2 regulates the G1-S transition and inhibition of its deacetylase activity drives cell cycle progression, it is possible that SIRT2 deacetylase activity serves a tumor-suppressive function." (PMID 37916830, 2023). "At this same 36-day time-point, whole-slide scans of liver segments stained with hematoxylin and eosin (H&E) confirmed that Sirt2−/− HCC mice had much smaller areas of neoplasia (areas of purple stain) compared to Sirt2+/+ HCC mice." (PMID 37628798, 2023). "Altogether, these data suggest that Sirt2 ablation is detrimental to tumor growth, which supports previous in vitro studies that showed Sirt2 functions as a tumor promotor." (PMID 37628798, 2023). "Most assays were performed in primary cells or diploid cell lines, because SIRT2 inhibition is antiproliferative or cytotoxic to many tumor cell lines." (PMID 37317966, 2023). "This approach opened exciting opportunities for future usage of selective SIRT2 inhibitors in overcoming poor clinical response to the TIL (tumor-infiltrating lymphocyte) or CAR-T (chimeric antigen receptor–T cell) immunotherapies." (PMID 36678624, 2023). "Evaluation of a novel transgenic mouse model of HCC provides evidence that Sirt2 functions as a tumor promotor in vivo." (PMID 37628798, 2023). "We found that SIRT2 protein levels were significantly increased in all tumor stages except stage I when compared with levels in adjacent tissues." (PMID 37115693, 2023). "Sirt2−/− HCC mice had smaller, less proliferative, and more differentiated liver tumors, suggesting that Sirt2 functions as a tumor promoter in this context." (PMID 37628798, 2023). "Significantly, mice deficient in Sirt2 develop breast, liver, and other cancers, suggesting that SIRT2 functions in tumor suppression." (PMID 35264593, 2022). "SIRT2 has varied expressions and can act as a tumor promoter or tumor suppressor based on the cell type." (PMID 36225477, 2022). "In tumorigenesis, the SIRT2 enzyme is known to exert a dual role, acting both as a tumor promoter and suppressor." (PMID 36297603, 2022). "Previous studies reported that SIRT2 mediates the acetylation of pyruvate kinase to regulate tumor growth." (PMID 35136826, 2022). "SIRT2 regulates mitosis, cell motility, differentiation, oxidative metabolism, and cell death, and it has tumor suppressor and oncogenic activities during tumorigenesis." (PMID 35054489, 2022). "The action of SIRT1 and SIRT2 is pivotal, depending on the type of tumor and the signaling pathway they affect." (PMID 35267521, 2022). "By comparing normal tissues using the TIMER2.0 database, we found high levels of SIRT2 expression in tumor tissues of CHOL, ESCA, KICH, KIRC and LIHC, while the converse is true in the case of KIRP, LUAD, LUSC, STAD and UCEC." (PMID 36844923, 2022). "In hepatocarcinoma, SIRT2 is upregulated and promotes vascular invasion, cell proliferation, and tumor growth." (PMID 35054489, 2022). "In vivo, inhibition of SIRT2 suppresses tumor growth and the metastatic potential of a GC cell line in nude mice." (PMID 36358890, 2022).